NRF1 (nuclear respiratory factor 1)
Diseases named in the same sentence as NRF1 in open-access papers (continued):
Sharing a sentence is not in itself a finding about the gene and the disease.
Cirrhosis (5 papers, 2016 to 2024). A chronic disorder of the liver in which liver tissue becomes scarred and is partially replaced by regenerative nodules and fibrotic tissue resulting in loss of liver function. "The results of Cox regression showed that cirrhosis (P = 0.018) and NRF1 expression (P = 0.004) correlated with survival of LIHC, and the TNM stage showed a strong tendency towards statistical significance (P = 0.052)." (PMID 35448958, 2022). "NRF1 showed a downward trend of expression in HCC compared with cirrhosis tissues." (PMID 37880213, 2023). "Thus, consistent with others, chronic HFFC diet intake induced MASH within a 24-week time frame, confirming that using this diet on these mouse lines is suitable for investigating the role of Nrf1 and Nrf2 in the progression of MASH to cirrhosis and HCC." (PMID 39125617, 2024). "The notion is also supported by altered Nrf1 expression in the para-carcinomas suffered from cirrhosis or not (cf. columns #1 with #5 and S6a with S6e)." (PMID 27065079, 2016). "By comparison of the data obtained from HCC samples #3 and #2, blunted expression of Nrf1 mRNAs, but neither the 140-kDa nor 120-kDa Nrf1α proteins, was indeed suggested to be relevant to additional lesion of cirrhosis." (PMID 27065079, 2016). "However, the study durations were insufficient to evaluate the impact hepatocyte Nrf1 and Nrf2 activity may have on more severe stages of MASLD, such as cirrhosis and HCC." (PMID 39125617, 2024).
colon carcinoma (5 papers, 2017 to 2023). "In conclusion, we found that Agr inhibited colon carcinoma progression by promoting oxidative stress and cell apoptosis by blocking the PGC-1α/NRF1/TFAM signaling pathway." (PMID 36591497, 2022). "We also examined the expression of genes and transcription factors in key metabolic signaling pathways across the subpopulation, the most abundant genes in colon cancer were PDK1, NRF1, MYC, and HIF1A." (PMID 35755820, 2022). "For example, we preliminarily found that NRF3 knockdown significantly induces NRF1 protein accumulation, which rescues loss of NRF3 function in human colon cancer HCT116 cells, although NRF1 knockdown does not induce NRF3 protein (data not shown)." (PMID 28970512, 2017).
glioblastoma (5 papers, 2022 to 2026). The most malignant astrocytic tumor (WHO grade IV). "NRF1 has been linked to glioma severity and poor prognosis in glioblastoma." (PMID 39990231, 2025). "NRF1 is associated with severity of astrocytoma and indicates poor prognosis of glioblastoma." (PMID 37875967, 2023). "In glioblastoma, NSUN2 is a target gene of nuclear respiratory factor 1 (NRF1), and its high expression is associated with resistance to temozolomide (TMZ) therapy." (PMID 35562754, 2022).
glioma (5 papers, 2021 to 2025). A benign or malignant brain and spinal cord tumor that arises from glial cells (astrocytes, oligodendrocytes, ependymal cells). "Thereby, we here explore the impact of such a key regulatory transcription factor NFE2L1 (also called Nrf1) on glioma‐relevant TAMs." (PMID 40677211, 2025).
Hyperglycemia (5 papers, 2019 to 2025). An increased concentration of glucose in the blood. "The expression of Nrf1 was significantly higher in ARPE-19 cells under hyperglycemia than in those cultured under normoglycemia, and CoPP significantly elevated the expression under both glucose conditions." (PMID 39857426, 2025). "In addition, the activation of Nrf2 may also promote mitochondrial biogenesis by positively regulating nuclear respiratory factor 1 and indirectly ameliorate hyperglycemia-induced oxidative stress." (PMID 31616304, 2019). "NRF-1 and PGC-1a have been observed to be reduced in hyperglycemia-induced skeletal muscle damage." (PMID 35432808, 2021). "However, under normoglycemia, CoPP treatment significantly upregulated the expressions of PGC-1α and NRF1 but downregulated the expressions of mtTFA—this thus justified CoPP treatment elevating mitochondrial respiration in ARPE-19 cells under hyperglycemia but not normoglycemia." (PMID 39857426, 2025).
cardiac hypertrophy (4 papers, 2021 to 2024). "In addition, EVO preserves mitochondrial function by increasing the activity of the PGC1α/NRF1/TFAM signaling pathway and inhibits the development of cardiac hypertrophy and fibrosis by attenuating TGFβ/IGFBP7/Col1a1 expression." (PMID 37009790, 2023).
Infertility (4 papers, 2019 to 2026). "Furthermore, a study describing the conditional loss of Nrf1 in testis implicated the loss of Asz1 (Gasz1) transcription as a causative factor in the infertility of these mice." (PMID 31350280, 2019). "However, in the literature, conditional ablation of Nrf1 in gonocytes has been shown to lead to infertility in male mice." (PMID 34359231, 2021). "A role for NRF1 during human spermatogenesis has also been suggested since mutations in the promoter regions of a key meiotic gene, DAZL, lead to the loss of NRF1 binding and are associated with infertility." (PMID 31350280, 2019).
ischemic stroke (4 papers, 2023 to 2025). A stroke disorder caused by obstruction of blood flow to the brain, due to thrombotic (local blood clot formation) or embolic (due to a blood clot or other material traveling from another site) event. "Through its regulation of mitochondrial function and redox balance, NRF1 provides neuroprotection in ischemic stroke, making it a potential therapeutic target." (PMID 40299522, 2025). "This contributes to a reduction in infarct volume and neuroinflammation (iNOS/Arg1, TNF-α, and IL-1β levels) after ischaemic stroke, and Nrf1 acetylation plays a crucial role in this process." (PMID 39198723, 2024). "Further elucidation of factors that regulate microglia and nuclear factor (erythroid-derived 2)-like 1 (Nrf1) may lead to a promising strategy for treating neuroinflammation after ischaemic stroke." (PMID 39198723, 2024). "In this study, we aimed to explore the protective effect of PTS against neurological deficits and secondary injury against ischaemic stroke through histone deacetylase 3 (HDAC3)/Nrf1-mediated microglial actions, which might facilitate further translational studies." (PMID 39198723, 2024). "Peroxisome proliferator-activated receptor gamma agonists can upregulate PGC-1α, NRF1, TFAM, and cytochrome c oxidase subunits I and IV and enhance mitochondrial biogenesis in ischemic stroke." (PMID 37033646, 2023). "Unlike reports indicating that HDAC3 directly mediates p65, our findings suggest that Nrf1 acetylation may serve as a link between HDAC3 and p65 interaction in microglia following ischaemic stroke." (PMID 39198723, 2024). "We found that PTS decreased HDAC3 expression and activity, increased Nrf1 acetylation in the cell nucleus and inhibited the interaction of Nrf1 with p65 and p65 accumulation, which reduced infarct volume and neuroinflammation (iNOS/Arg1, TNF-α and IL-1β levels) after ischaemic stroke." (PMID 39198723, 2024).
ovarian carcinoma (4 papers, 2016 to 2022). A malignant neoplasm originating from the surface ovarian epithelium. "Proteasome components exhibit coordinate regulation mediated by Nrf1 signaling in response to partial proteasome inhibition, and we have described their upregulation in ovarian cancer in association with ubiquitin-proteasome system (UPS) stress and increased metabolic burden." (PMID 28784174, 2017). "MIR502, which is regulated by NRF1, acts as a tumour suppressor gene to accelerate apoptosis and suppress proliferation by targeting the Hippo signalling pathway in ovarian cancer." (PMID 32660514, 2020). "The elevated expression of haemoxygenase, which is an Nrf1/2 dependent gene, as a result of PB treatment in BRCA1 blocked BG1 ovarian cancer cell has also been reported earlier by our own group, confirming the activation of the antioxidant mechanism." (PMID 27220670, 2016).
pancreatic cancer (4 papers, 2017 to 2024). "Further investigation will be required to determine the significance of Nrf1 signaling in pancreatic cancer." (PMID 29190947, 2017). "This suggests that on a transcriptional level, Nrf1 expression may also be induced in pancreatic cancer and available to induce Prdx1 expression in pancreatic cancer." (PMID 29190947, 2017). "This could have interesting consequences on regulation of ARE mediated transcription in pancreatic cancer because Nrf1 can both support Nrf2 function and suppress ARE mediated transcription depending on the Nrf1 isoform being expressed." (PMID 29190947, 2017). "While Nrf2 expression may be elevated in pancreatic cancer because of differences in its post-translational regulation and degradation in cancer, changes in Nrf1 mRNA levels could indicate differences in its overall expression or the transcription of an Nrf1 splice variant." (PMID 29190947, 2017). "Experimental evidence found that pancreatic cancer cell-derived exosomes enriched with GOT1 inhibited cellular ferroptosis to promoted pancreatic cancer cell progression through mechanisms like upregulating CCR2 expression and activating the Nrf1/HO2559-1 pathway." (PMID 39777342, 2024). "Interestingly, we found that Prdx1 mRNA was significantly elevated in human pancreatic cancer tissue, which correlated with increased Nrf1 mRNA expression but not with Nrf2 mRNA expression." (PMID 29190947, 2017).
Stroke (4 papers, 2012 to 2024). Sudden impairment of blood flow to a part of the brain due to occlusion or rupture of an artery to the brain. "Consequently, Nrf1 has emerged as a promising therapeutic target for stroke." (PMID 39198723, 2024). "The significant increase of NRF1 expression level was 20% (p < 0.01), that of TFAM was 50% (p < 0.01), that of NDUFV2 was 20% (p < 0.01), that of SDHA was 50% (p < 0.01), and that of VEGF was 40% (p < 0.01), compared to the Stroke + Saline group." (PMID 33806692, 2021). "In our stroke model, we observed a pronounced short-term PGC-1α activation, evidenced by a significant upregulation of PGC-1α-dependent proteins: NRF1, TFAM, catalytic subunits of the substrate-binding sites of the respiratory chain (NDUFV2 and SDHA), VEGF, and SYP." (PMID 33806692, 2021). "Therefore, we explored if selenium pretreatment could increase the levels of mitochondrial biogenesis regulators, NRF1 and PGC-1α, in in vivo stroke model." (PMID 22776356, 2012).
astrocytoma (3 papers, 2021 to 2023). "Recently, it was shown that increased nuclear respiratory factor 1 (NRF1) transcription factor activity in astrocytoma is associated with poor survival." (PMID 38136601, 2023).
cardiomyopathy (3 papers, 2017 to 2024). A disease of the heart muscle or myocardium proper. "Given that Dox-induced cardiomyopathy in cancer patients carries poor prognosis and is frequently fatal, we next studied whether NRF1 overexpression confers cardioprotection against Dox in hPSC-CMs." (PMID 34489413, 2021).
cutaneous melanoma (3 papers, 2019 to 2025). A primary melanoma arising from atypical melanocytes in the skin. "We characterized the immunohistochemical expression of NRF1 and NRF2 in 99 naevi, 88 primary skin melanomas, and 67 lymph node metastases." (PMID 31687076, 2019).
endometrial cancer (3 papers, 2021 to 2022). Primary or metastatic malignant neoplasm involving the endometrium (mucous membrane that lines the endometrial cavity). "High NRF1 expression is a good prognostic factor in renal and endometrial cancer; however, NRF1 remains to be investigated in a NSCLC cohort (Human Protein Atlas)." (PMID 36359002, 2022). "Metapristone decreased the expression of miR-492 and its target genes Klf5 and Nrf1, leading to endometrial cancer cell growth inhibition in vitro and in vivo." (PMID 33413440, 2021). "Secondly, the mechanical relationship between Klf5/Nrf1 and cell proliferation or apoptosis with the treatment of metapristone on endometrial cancer has still indistinct." (PMID 33413440, 2021). "Taken together, all the results showed that metapristone inhibited the endometrial cancer cell growth in vitro and in vivo through regulating miR-492/Klf5/Nrf1 axis and the cell apoptosis-related signaling pathways." (PMID 33413440, 2021). "More importantly, this study suggested that metapristone inhibited endometrial cancer cell growth via miR-492/Klf5/Nrf1 axis, which provided a new mechanism of antitumor effect of metapristone on endometrial cancer for the clinical application." (PMID 33413440, 2021). "Mechanically, miR-492 and its target genes Klf5 and Nrf1 were highly expressed in the endometrial cancer cell lines, which promoted cell proliferation and inhibited cell apoptosis." (PMID 33413440, 2021). "Mechanically, metapristone regulated miR-492 and its new target genes Klf5 and Nrf1 in vitro and in vivo to treat endometrial cancer." (PMID 33413440, 2021). "Metapristone inhibited the endometrial cancer cell growth through regulating the cell apoptosis-related signaling pathway and decreasing the expression of miR-492 and its downstream target genes (Klf5 and Nrf1), which provided the theoretical basis in clinical treatment of endometrial cancer." (PMID 33413440, 2021).
fibrosis (3 papers, 2021 to 2026). the formation of excess fibrous connective tissue in an organ or tissue in a reparative or reactive process. "In conclusion, we identified distinct and complementary roles for hepatocyte Nrf1 and Nrf2 in protecting against MASLD progression and in promoting hepatocyte regeneration in liver with MASH-linked fibrosis." (PMID 39125617, 2024). "Here, we explored this possibility using a validated model of diet-induced MASH on transgenic mice amenable to adult-onset loss-of-function for hepatocyte Nrf1, Nrf2, or both and by enhancing the actions of Nrf1, Nrf2, or both in wild-type mice with MASH-linked fibrosis." (PMID 39125617, 2024). "Using similar methods to induce Nrf1 and Nrf2, here we investigated whether more prolonged induction of Nrf1, Nrf2, or both may alleviate MASH and fibrosis in a MASH-linked fibrosis model." (PMID 39125617, 2024). "Then Nrf1 protein levels were assessed in three liver fibrosis models of mice including HFD-induced, CCl4-induced and BDL-induced fibrosis." (PMID 41424862, 2026).
mesothelioma (3 papers, 2016 to 2022). A usually malignant and aggressive neoplasm of the mesothelium which is often associated with exposure to asbestos. "In a previous study we demonstrated a strong positive correlation between calretinin mRNA and protein levels in mesothelioma cell lines and demonstrated NRF-1 and E2F2 to act as transcription factors regulating calretinin expression." (PMID 28611824, 2017). "In the present study we found cis-regulatory sequence elements that are essential for calretinin expression in mesothelioma cells, and identified NRF-1/E2F2 as transcription factors binding to this regulatory sequence." (PMID 26848772, 2016). "For all these reasons and since we observed similar expression of NRF-1 in a panel of mesothelioma cell lines with different calretinin expression levels, it is most likely that NRF-1 is a part of a protein complex that altogether activates calretinin expression." (PMID 26848772, 2016). "The present results indicate that α-T3E acts as an effective anti-mesothelioma agent by disrupting the homeostasis of proteasomes through the simultaneous inactivation of STAT3 and NRF1." (PMID 35269802, 2022). "A strongly reduced activity of the E2F2/NRF-1 mutant construct was also observed in HEK293 cells, indicating that this transcriptional control is not restricted to mesothelioma cells, but possibly to other cells of mesodermal origin." (PMID 26848772, 2016).
schizophrenia (3 papers, 2021 to 2025). A major psychotic disorder characterized by abnormalities in the perception or expression of reality. "Finally, we provided evidence for the molecular mechanism of the binding between rs1399178 and NRF1, further validating the characteristic of NRF1 in recognizing specific DNA sequences and offering new insights into investigating schizophrenia susceptibility loci." (PMID 40019038, 2025). "The identification of rs1399178 as a bifunctional regulatory element, mediating promoter‐enhancer switch and interacting with NRF1, sheds light on the complex regulatory networks involved in schizophrenia pathogenesis." (PMID 40019038, 2025). "The combination of genomics, functional assays, structural analysis, and in‐depth exploration of NRF1's recognition mechanisms provide a comprehensive framework for future research into the genetic mechanisms of schizophrenia and potential therapeutic interventions." (PMID 40019038, 2025).
status epilepticus (3 papers, 2019 to 2023). Status epilepticus is defined as a continuous seizure lasting more than 30 min, or two or more seizures without full recovery of consciousness between any of them. "Furthermore, resveratrol promoted mitochondrial biogenesis in a rat model of status epilepticus, by increasing protein expression of PGC-1α, NRF1, TFAM, as well as the mtDNA, and attenuation of neuronal cell damage in the hippocampus following status epilepticus." (PMID 36237161, 2023).
urothelial carcinoma (3 papers, 2019 to 2024). A malignant neoplasm derived from the transitional epithelium of the urinary tract (urinary bladder, ureter, urethra, or renal pelvis). "Expanding our scope to include other solid cancers, based on a case report of urothelial carcinoma featuring a NRF1–BRAF fusion that demonstrated a clinical response to trametinib, we have enrolled a patient with renal pelvis cancer harboring NRF1–BRAF fusion into the belvarafenib EAP program." (PMID 38470950, 2024). "The NRF1-BRAF fusion gene was previously detected in 2 cases of anaplastic pleomorphic xanthoastrocytoma (PXA) and urothelial carcinoma." (PMID 38476985, 2024).
alcoholic steatohepatitis (2 papers, 2022 to 2023). "Disruption of the NRF‐1‐TFAM pathway was recently shown to contribute to mitochondrial dysfunction and liver damage in alcoholic steatohepatitis." (PMID 36101976, 2022).
anemia (2 papers, 2020 to 2025). A reduction in the number of red blood cells, the amount of hemoglobin, and/or the volume of packed red blood cells. "The Nrf1-/- embryos died in utero of decreased definitive enucleated red cells and the ensuing anemia, which results from impaired maturation of erythroid progenitors in the microenvironments of the foetal liver, but without increased apoptosis of the haematopoietic cells." (PMID 40703332, 2025).
Anxiety (2 papers, 2024). Intense feelings of nervousness, tension, or panic often arise in response to interpersonal stresses. "Unsaturated fatty acids interact with membrane phospholipids to form structural modifiers, which increase membrane flow and permeability, help regulate NRF1/HMOX1 signaling pathway, reduce oxidative stress in vivo, and relieve anxiety symptoms." (PMID 38547138, 2024).
brain injury (2 papers, 2021 to 2024). Acute and chronic (see also brain INJURIES, CHRONIC) injuries to the brain, including the cerebral hemispheres, CEREBELLUM, and brain STEM. "Elevated levels of cyclin D1 (CD1) following brain trauma suppress the acetylation of nuclear respiratory factor 1 (NRF1), reducing its transcriptional activity and leading to a decrease in mtDNA content." (PMID 39133904, 2024). "Previous studies reported that neural mitochondrial biogenesis regulators (e.g., PGC-1α, TFAM, NRF-1, and NRF-2) were upregulated as a compensatory response to energy demand and reductions in neural mitochondrial content in I/R-induced brain injury." (PMID 35002619, 2021).
breast invasive carcinoma (2 papers, 2018 to 2022). "Whilst the molecular mechanism by which NRF1 may contribute to an individual’s susceptibility to invasive breast cancer is not clear, we are beginning to acquire tantalizing evidence." (PMID 30486409, 2018). "This highly novel role of NRF1 in the stochastic acquisition of BCSC-like subsets and their progression to a malignant phenotype may open an entirely new research direction targeting NRF1 signaling in invasive breast cancer." (PMID 30486409, 2018).